HNRNPK (heterogeneous nuclear ribonucleoprotein K)
Diseases named in the same sentence as HNRNPK in open-access papers (continued):
Sharing a sentence is not in itself a finding about the gene and the disease.
cancer (continued). "A total of 12 splicing factors were significantly associated with the OS of KIRC, among which splicing factors such as PCBP1, hnRNPK and hnRNPM were engaged in tumorigenesis through guiding alternative splicing programs in various cancers 31-33." (PMID 32047561, 2020). "One example of upregulated lncRNA in colon cancer is the c-Myc-regulated lncRNA called MYCLo-2, which represses p21 transcription by interacting with hnRNPK, and plays a crucial role in cancer transformation and tumorigenesis." (PMID 30658384, 2019). "Recently, hnRNPK has been reported to interact with several lncRNAs and to regulate their functions in cancer." (PMID 31110205, 2019). "Human heterogeneous nuclear ribonucleoprotein K (hnRNPK) is a member of the hnRNP family and has been frequently been observed to show abnormal expression in many human cancers." (PMID 31110205, 2019). "We first analyzed the expression pattern of hnRNPK mRNA in a total of 374 clinical samples of GC and 47 normal controls in TCGA (the Cancer Genome Atlas) datasets." (PMID 31857793, 2019). "Taken together, SLINKY appears to be a novel lncRNA that is upregulated across several malignancies and that drives aggressiveness in ccRCCs by regulating cancer cell proliferation through the recruitment of hnRNPK." (PMID 30658384, 2019). "Many scientists have focused on HNRNPK and attempted to reveal the role of HNRNPK in cancer progression." (PMID 31942561, 2019). "HNRNPK is a crucial RNA and DNA binding protein and reported function as a crucial regulator for the progression of human cancers (Barboro, Ferrari, & Balbi, 2014)." (PMID 31429522, 2019). "HNRNPK has been reported to associate with CDK9 and XRN2 in cancer cells to potentially regulate transcription elongation and termination, respectively." (PMID 31519929, 2019). "For instance, HNRNPK overexpression is related to tumorigenesis in several cancers, whose binding motif RNCMPT00026 is matched with KER_959 learnt by CSCRSites." (PMID 31703384, 2019). "Overall, we established a new model in which HNRNPK expression in cancer cells was specifically downregulated and downregulation of HNRNPK significantly inhibited lung metastasis." (PMID 31942561, 2019). "This knowledge will aid in the development of novel therapeutic strategies to target hnRNPK in many types of cancer and other diseases in the future." (PMID 30836866, 2019). "Here, the authors identify 633 prognostic markers, 570 S-phase cancer-associated lncRNAs, and show SCAT7 regulates FGF/FGFR and PI3K/AKT/MAPK pathways via interaction with hnRNPK/YBX1 complexes." (PMID 29491376, 2018). "It is possible that hnRNPK up-regulates the c-FLIP protein levels in cancer cells through other mechanisms." (PMID 29724888, 2018). "And FLIP, FGF2, SULF2 and MMP13 are known to be overexpressed in various cancers and downstream of hnRNPK." (PMID 28423622, 2017). "In our study, we find that SLINKY enhances cancer cell proliferation most likely through its interaction with HNRNPK." (PMID 28423633, 2017).
cancer (continued). "Over the past decade, in vitro and biochemical studies had shown that HNRNPK was involved in many cellular processes, which were crucial for tumorigenesis and cancer development." (PMID 29262567, 2017). "Knock-down of hnRNPK results in strongly reduced migratory activity of cancer cells, strongly suggesting hnRNPK as a promising target molecule for cancer progression." (PMID 27832777, 2016). "In combination with existing reports and GBP1-regulated AS events, a regulatory pathway was finally obtained, that is, GBP1 regulated CD44 protein expression through A3SS alternative splicing after binding to HNRNPK, and finally played a role in promoting cancer." (PMID 38167153, 2024). "Identification of genes involved in promoting cancer and cell migration is a strong indication that transcriptomic changes of those genes significantly contribute towards K19-dependent cell proliferation and cytoplasmic HNRNPK-dependent cancer metastasis." (PMID 37592256, 2023). "Together, all these observations suggest that HNRNPK might perform its complex functions in multiple ways in different cancer contexts." (PMID 36681772, 2023). "However, we found that HNRNPK shows common essentiality across all cancer cell lines in the DepMap42." (PMID 36681772, 2023). "Likewise, HNRNPK has been shown to be involved in DNA damage and has been broadly studied in the context of cancer research." (PMID 35895140, 2022). "HnRNPK is highly expressed in numerous cancer tissues and can promote EMT." (PMID 35461306, 2022). "In NSCLC, the nuclear HNRNPK can promote the epithelial mesenchymal transition of cancer cells." (PMID 36439880, 2022). "HnRNPK is known to be one of the most promising RBP targets for the treatment of various cancers." (PMID 33731671, 2021). "Our discovery of the potential crosstalk between the DDX3 and hnRNPK cascades may provide a new strategy for apoptosis induction in cancer cells." (PMID 34575922, 2021). "The detailed mechanism regarding how hnRNPK switches between its apoptosis-promoting and suppressive roles in cancer cells remains unclear." (PMID 34575922, 2021). "While hnRNPK is a multi‐functional nuclear protein with known healthy and disease functions, this study provides the first documented role of exosomal hnRNPK and its direct interaction with miRNA in cancer." (PMID 33931969, 2021). "Aberrant expression and localization of hnRNPK, commonly observed in cancer, could thus also play a role in the change of MALAT1 localization in HCC." (PMID 32340118, 2020). "Thus, the deregulation of hnRNPK in cancer has far-reaching ramifications as it affects the function and localization of lncRNAs." (PMID 32340118, 2020). "HnRNPK is an essential RNA- and DNA-binding protein that plays a critical role in several cancers." (PMID 31221168, 2019). "Likewise, we herein have presented a similar phenomenon where by arginine methylation permits hnRNPK to play a similar dual role regarding the regulation of cancer cell migration." (PMID 31110205, 2019). "Downregulation of HNRNPK in cancer cells can inhibit lung metastasis." (PMID 31942561, 2019). "Thus, it is critical to understand the mechanism of hnRNPK regulation and its downstream effects on cancer and other diseases." (PMID 30836866, 2019).
cancer (continued). "In addition, hnRNPK is known to be involved in anti-apoptosis, angiogenesis, proliferation, and the metastasis of cancer cells." (PMID 31110205, 2019). "Interestingly, SLINKY enhances cancer cell proliferation—most likely through its interaction with hnRNPK." (PMID 30658384, 2019). "Similarly, ERK-dependent cytoplasmic accumulation of hnRNPK was upregulated in many human cancers and was involved in the antagonism of cancer cell apoptosis." (PMID 30836866, 2019). "Regardless, our study along with others suggests that lncRNA recruitment of HNRNPK might serve as a generalized mechanism to affect the gene expression changes that drive cancer." (PMID 28423633, 2017). "Thus, SLINKY is a robust prognostic biomarker in ccRCC, where it functions possibly together with HNRNPK in cancer cell proliferation." (PMID 28423633, 2017). "hnRNPK overexpression is related to tumorigenesis in several cancers." (PMID 27862976, 2017). "Furthermore, by exploring CTD base, several ways to repress cancer progression through upregulating HNRNPK expression were suggested." (PMID 29262567, 2017). "The hnRNPK/miR-223/FBXW7 feedback loop may represent a previously uncharacterized mechanism in PDAC cancer patients." (PMID 28423622, 2017). "Moreover, in all cancer tissues examined, hnRNPK was found in the cytoplasm whereas it is exclusively nuclear in the normal tissues." (PMID 26972480, 2016). "Finally, we evaluated hnRNPK prognostic values in pan-cancer." (PMID 37639158, 2023). "Mechanistic investigations on one of the top S-phase enriched cancer associated lncRNAs SCAT7 (ELF3-AS1) revealed that it promotes tumorigenesis through activating fibroblast growth factor (FGF/FGFR)-dependent PI3K/AKT and MAPK pro-survival pathways via interacting with hnRNPK/YBX1 complex." (PMID 36230680, 2022). "By isolating primary cancer-associated fibroblasts (CAFs) from human LUAD, we confirmed that decreased extracellular CLCN3 secretion induced by HNRNPK knockdown inhibited CAFs activation and TGF-β1 production, thus suppressing nuclear HNRNPK expression and LUAD progression in a feedback way." (PMID 36439880, 2022). "Compared with FHC cells, we showed that high expression of hnRNPK reduced the cancer cell proliferation, so we speculated that the patients with higher hnRNPK levels might have lower cell proliferation rates and stronger immune infiltrations, thus prolonging their survival times." (PMID 35875075, 2022). "However, the upregulation of hnRNPK is correlated with cancer transformation, progression, and migration, whereas the regulatory role of hnRNPK in cancer malignancy remains unclear." (PMID 34575922, 2021). "Finally, we went on to measure hnRNPK EV protein in cancer biofluids." (PMID 33931969, 2021). "Taken together, the SCAT7/hnRNPK/YBX1 RNP complex plays a crucial role in carcinogenesis, and SCAT7 may be used as a prognostic marker in risk assessments as well as potential therapeutic regimens in the treatment of cancer." (PMID 30658384, 2019). "Whether hnRNPK is regulated through a similar mechanism in other cancers needs further evaluation." (PMID 28423622, 2017). "Finally, we found that in 52 (100%) carcinoma tissues examined, hnRNPK could be found in both the cytoplasm and nucleus whereas it was exclusively nuclear in normal tissues." (PMID 26972480, 2016). "We previously demonstrated that RNA-binding domains of hnRNPK, hnRNPU, and RBM39 act as dominant-negatives and reduce cancer cell growth and viability." (PMID 38349913, 2024). "KEGG pathway enrichment was performed on 74 target genes using DAVID, and four genes, BMPR2, HMOX1, HNRNPK and ZEB1, were enriched on the “microRNAs in cancer” signal pathway." (PMID 38693503, 2024).
cancer (continued). "We believe that GBP1 and HNRNPK bind to regulate the expression of CD44 protein through A3SS alternative splicing form, and finally play a role in promoting cancer." (PMID 38167153, 2024). "Furthermore, hnRNPK is overexpressed in the nuclei and cytoplasm of several types of cancer cells, including head-and-neck/oral squamous cell carcinomas (SCCA), and its aberrant cytoplasmic localization is associated with a poor prognosis, suggesting its involvement in cancer progression." (PMID 33806648, 2021). "Targeting of CARF by Snol-A also caused (i) downregulation of pATR-Chk1 signaling leading to caspase-mediated apoptosis and (ii) inactivation of β-catenin/Vimentin/hnRNPK-mediated EMT signaling resulting in decrease in migration and invasion of cancer cells." (PMID 32286347, 2020). "Mechanistic investigations on SCAT7 in multiple cancer types using chromatin oligo-affinity precipitation (ChOP) and RNA immunoprecipitation (RIP) assays reveal that it interacts with the hnRNPK/YBX1 complex." (PMID 30658384, 2019). "Whereas Wi-A binds to vimentin and heterogeneous nuclear ribonucleoprotein K (hnRNP-K) with high efficacy and downregulates its effector proteins, MMPs and VEGF, involved in cancer cell metastasis, 3βmWi-A was ineffective." (PMID 31757995, 2019). "Taken together, these observations indicate that SCAT7/hnRNPK/YBX1 RNP plays a crucial role in the transcriptional activation of FGFR2 and/or FGFR3 in different cancer models." (PMID 29491376, 2018). "Mechanistic investigations on SCAT7 in multiple cancer types reveal that it interacts with hnRNPK/YBX1 complex and affects cancer cell hallmarks through the regulation of FGF/FGFR and its downstream PI3K/AKT and MAPK pathways." (PMID 29491376, 2018). "Three genes emerged: TARDP (Transcription of RNA activating protein/TAR DNA binding protein); HNRNPK (Heterogeneous Nuclear Ribonucleoprotein K); and WDR33 (WD Repeat Domain 33) as having the lowest CVs across the spectrum of cancers." (PMID 29088295, 2017). "Our recent investigations on RBM39-RRM3-, SAFA-RGG- and hnRNPK-RGG- derived cell-penetrating peptides revealed that treating cells with a penetratin-tagged peptide from these functional domains inhibited cancer cell growth and survival." (PMID 38349913, 2024). "We also found that HNRNPK might co-regulate downstream target genes with MYC, and play important roles in cancer." (PMID 36681772, 2023). "While cytoplasmic accumulation has been correlated with cancer, no mechanistic insights regarding how cytoplasmic hnRNPK is regulated or how it functions in a pro-tumorigenic pathway have been provided." (PMID 36329064, 2022). "In FHC cells, the interaction between hnRNPK and hnRNPA1/R/U proteins was observed, which revealed that the hnRNPK/A1/R/U interaction was not specific to cancer cells." (PMID 35875075, 2022). "In contrast, in cancer cells lacking Fbxo4 or/and αB-crystallin, unmodified hnRNPK recruits c-Myc mRNA and supports its efficient translation." (PMID 36329064, 2022). "DDX3 is an RNA helicase that is involved in cancer development and apoptosis, whereas whether the helicase activity of DDX3 affects its interaction with hnRNPK remains unknown." (PMID 34575922, 2021). "Next, we compared expression of TARDP, HNRNPK, and WDR33 in different cancers." (PMID 29088295, 2017). "Indeed, K17 interacts with HNRNPK and HNRNPS1 proteins have been shown to interact with a type III intermediate filament protein vimentin, which is upregulated in several cancers and plays a critical role in metastasis." (PMID 37592256, 2023). "Therefore, the hnRNPK-mediated transcription and translation processes are specific to cancer cells but not to the normal cells." (PMID 35875075, 2022).
cancer (continued). "Therefore, hnRNPK-mediated PTOV1-AS1 regulation acts as a decoy for miR-1207-5p to modulate HMOX1 expression, which plays a critical role in the proliferation and metastasis of various cancers." (PMID 30658384, 2019). "In addition, hnRNPK is involved in multiple types of cancers where it is often aberrantly expressed compared with the normal tissue cells, and also essential for cancer metastasis by inducing cell movement, angiogenesis and extracellular matrix modifying genes 23-26." (PMID 35342346, 2022). "The CVs were 0.095, 0.106, and 0.109 for TARDP, HNRNPK, and WDR33, respectively, reflecting variability in gene expression across different categories of cancer that was no greater than the variability observed in different specimens of the same malignancy." (PMID 29088295, 2017). "HNRNPK exhibited higher activities in CRC, LC and OvC cancer cells but not in BRCA." (PMID 36681772, 2023).
infection (24 papers, 2013 to 2025). The state of being infected such as from the introduction of a foreign agent such as serum, vaccine, antigenic substance or organism. "Subsequent validation experiments confirmed that hnRNPK was significantly upregulated in gastric epithelial cells following infection with H. pylori 26695, compared to the ΔSlyD strain and the blank group." (PMID 39915880, 2025). "However, the impact of hnRNPK in H. pylori SlyD infection within the context of GIM remains unexplored." (PMID 39915880, 2025). "Our findings suggest that lncSSBP1 may affect IL-6 mRNA expression during TM infection through interaction with hnRNPk in bronchial epithelial cells." (PMID 31998294, 2019). "The correlation among hnRNPK/TPT1/OCT1, GIM, and H. pylori SlyD infection was further validated in human and Mongolian gerbils (MGs) gastric tissues." (PMID 39915880, 2025). "To study the function of hnRNPK in vitro, we established stable hnRNPK-knockdown and hnRNPK-overexpressed cell lines (HCT116, SW480, and FHC) by lentiviral infection." (PMID 35875075, 2022). "Additionally, IHC staining of human and MGs gastric tissues revealed a correlation between hnRNPK, TPT1, GIM, and H. pylori SlyD infection." (PMID 39915880, 2025). "Early studies based on the nuclear yeast two-hybrid system method screened the interaction of heterogeneous nuclear ribonucleoprotein K (hnRNP-K) with ASFV p30, which may be involved in the downregulation of host cell mRNA translation after ASFV infection." (PMID 36090090, 2022).
neurodegenerative disease (5 papers, 2021 to 2026). A disorder of the central nervous system characterized by gradual and progressive loss of neural tissue and neurologic function. "However, some of these RBPs employ other mechanisms, such as HNRNPK which stabilizes RNA by preventing inclusion of cryptic exons during alternative splicing–a process that is critical in several neurodegenerative diseases." (PMID 39236079, 2024).
head and neck tumors (1 paper, 2015). "Previous studies have shown that hnRNPs played central roles in several cellular functions, among which HNRNPK was found to play an essential role in cellular proliferation by regulating protein synthesis and is over-expressed in head and neck tumors." (PMID 25866482, 2015).
HNRNPK also shares sentences with these, for which no sentence is quoted: hematologic malignancies (6 papers); neurodevelopmental disorder (5); Alzheimer disease (4); Burkitt lymphoma (4); cholangiocarcinoma (4); frontotemporal lobar degeneration (4); Multiple myeloma (4); HIV-1 infection (3); lymph node metastasis (3); B-cell lymphoma (2); diffuse large B-cell lymphoma (2); esophageal cancer (2); esophageal squamous cell carcinoma (2); head and neck squamous cell carcinoma (2); hematological neoplasms (2); influenza (2); renal carcinoma (2); renal cell carcinoma (2); Renpenning syndrome (2); acute lymphoblastic leukemia (1); aplastic anemia (1); atrioventricular septal defect (1); B-cell neoplasm (1); Bicuspid aortic valve (1); breast tumors (1); chronic myeloid leukemia (1); Cirrhosis (1); colitis (1); colorectal tumours (1); corticobasal degeneration (1).
A further 34 diseases each share a sentence with HNRNPK in 1 paper.